NOD2 (nucleotide binding oligomerization domain containing 2)
Diseases named in the same sentence as NOD2 in open-access papers (continued):
Sharing a sentence is not in itself a finding about the gene and the disease.
ischemic stroke (4 papers, 2019 to 2024). A stroke disorder caused by obstruction of blood flow to the brain, due to thrombotic (local blood clot formation) or embolic (due to a blood clot or other material traveling from another site) event. "RIP2 inhibitors targeting the downstream of NOD2 signaling is a potential treatment for inflammatory conditions associated with ischemic stroke." (PMID 38012669, 2023). "In summary, we have found that NOD2 stimulation mediated robust and broad inflammatory response in microglia and ARRB2 negatively regulated NOD2‐induced inflammatory response following ischaemic stroke by combination with TRAF6." (PMID 30793522, 2019). "Moreover, the molecular mechanism of inflammatory damage in ischemic stroke mediated by NOD2 targeted NOX2-dependent oxidative stress." (PMID 38012669, 2023). "Previous studies have shown that naringenin could attenuated diabetic neuropathic pain by modulating the expression of MMP-9, and may have protective effect on ischemic stroke by down-regulating the expression of NOD2, RIP2, NF-κB, MMP-9." (PMID 37270490, 2023). "Taken together, ARRB2 emerged as an important control point in the integration of inflammatory responses mediated by NOD2, which may prove useful in the future development of new therapeutic approach for the treatment of ischaemic stroke." (PMID 30793522, 2019).
lung disease (4 papers, 2013 to 2021). "It was found that the physiological role of NOD2 in antiviral defense was the enhanced respiratory syncytial virus pathogenesis, lung disease, and greater viral susceptibility through the study of NOD2‐deficient mice." (PMID 30950247, 2019). "However, the contribution of NOD2 to lung disease has yet to be reported." (PMID 29560100, 2018). "The importance of NOD2 in antiviral defenses was shown by the increased body weight loss, decreased type I IFN production and increased proinflammatory cytokine and chemokine production, enhanced lung disease and virus susceptibility of NOD2-deficient mice infected with RSV, compared to wild type." (PMID 24244872, 2013).
meningitis (4 papers, 2016 to 2023). A disorder characterized by acute inflammation of the meninges of the brain and/or spinal cord. "For meningitis outcome the rs2067085 in NOD2 (p = 5.1e − 04) and rs4251552 of IRAK4 were the strongest associations with unfavorable outcome (p = 6.7e − 04)." (PMID 27432718, 2016). "Bacterial infections leading to meningitis influence BBB permeability by allowing flow of molecules such as albumin, nucleotide-binding oligomerization domain 2 (NOD2) and inflammatory factors." (PMID 39484675, 2022).
myocarditis (4 papers, 2018 to 2022). Myocarditis is a condition that is characterized by inflammation of the heart muscle (myocardium). "The mRNA levels for the cytoplasmic pattern recognition receptor NOD2 (nucleotide-binding oligomerization domain 2) have been shown to be upregulated in patients infected by CV-B3 and suffering from myocarditis." (PMID 32704466, 2020). "The relevance of NOD2 expression in CVB3 myocarditis further followed from NOD2−/− CVB3 mice which were rescued from the detrimental effects of CVB3." (PMID 29434214, 2018). "While CVB3 replication could directly injure the myocardium, the excessive host immune response can also be activated by the recognition of CVB3 and NOD2 (nucleotide-binding oligomerization domain-containing protein 2), which plays a critical pathogenic role during CVB3-induced myocarditis." (PMID 34093086, 2021). "Our present findings which indicate a potent inhibitory effect of MSC on cardiac CVB3-induced NOD2 gene expression might therefore only be limited to the pathology of CVB3-induced myocarditis, and not generalized for all myocarditis etiologies." (PMID 29434214, 2018).
osteoporosis (4 papers, 2013 to 2025). A condition of reduced bone mass, with decreased cortical thickness and a decrease in the number and size of the trabeculae of cancellous bone (but normal chemical composition), resulting in increased fracture incidence. "Taken together, these data support screening of osteoporosis in pediatric onset CD, especially in children with NOD2 variants, low BMI and high PCDAI." (PMID 23635032, 2013). "We here demonstrate greater influence of NOD2 variants in pediatric-onset CD patients towards higher disease activity, risk for underweight, osteoporosis and more intensive immunosuppressive therapy." (PMID 23635032, 2013). "This is the first study identifying an influence of NOD2 variant alleles in patients with CD on osteoporosis and an age of onset dependent risk for steroid dependent or refractory course, long-term use of immunosuppressive drugs." (PMID 23635032, 2013). "Multivariate analysis demonstrated a 2.4 times increased risk for osteoporosis in CD patients carrying any NOD2 variant allele (p=0.02)." (PMID 23635032, 2013). "Osteoporosis was associated with patients carrying NOD2 variant alleles (p=0.033) and pediatric-onset of CD (p=0.022)." (PMID 23635032, 2013). "Especially pediatric onset CD patients with homozygous NOD2 variant alleles are prone to osteoporosis and osteopenia (p=0.037) and lower Z-scores respectively (p=0.033)." (PMID 23635032, 2013). "Therefore, multicentered studies on different populations and in different gene regions in larger samples are required to establish the correlation between the NOD1/CARD4 and NOD2/CARD15 polymorphisms and osteoporosis." (PMID 32578848, 2020). "The first time we thought that the functional polymorphisms in NOD1/CARD4 and NOD2/CARD15 genes might have triggered the development of osteoporosis." (PMID 32578848, 2020). "We thought that the functional polymorphisms in NOD1/CARD4 and NOD2/CARD15 genes might have triggered the development of osteoporosis." (PMID 32578848, 2020). "Interestingly, CD patients carrying NOD2 variant alleles have an increased risk towards osteoporosis." (PMID 23635032, 2013). "Interestingly, osteoporosis was found more frequently in patients carrying NOD2 variant alleles (p=0.033), especially in pediatric-onset CD patients with homozygous NOD2 variants (p=0.037)." (PMID 23635032, 2013). "In our study examined for the first time, relationship of the NOD1/CARD4 and NOD2/CARD15 polymorphism, which have a role in innate immune response with osteoporosis in Turkish women." (PMID 32578848, 2020). "The present study was aimed to investigate the relationship between NOD1/CARD4 and NOD2/CARD15 gene polymorphisms and osteoporosis in the Turkish population." (PMID 32578848, 2020). "The NOD1/CARD4 (rs5743336) and NOD2/CARD15 (rs2066847) SNPs were analyzed by PCR restriction fragment length polymorphism (PCR-RFLP) in 94 healthy controls and 164 subjects with osteoporosis." (PMID 32578848, 2020). "Furthermore, pre- or post-treatment of MDP alleviates RANKL-induced osteoporosis via NOD2 signaling." (PMID 34071605, 2021). "Our results suggest that the polymorphisms observed in the NOD1/CARD4 and NOD2/CARD15 genes are not genetic susceptibility factors for osteoporosis disease in Turkish women." (PMID 32578848, 2020). "The objective of our study was to determine the relationship between NOD1/CARD4 and NOD2/CARD15 SNPs and osteoporosis." (PMID 32578848, 2020). "However, we could not prove our hypothesis that osteoporosis is significantly more frequent in pediatric-onset CD patients carrying any NOD2 variant allele may be due to a lack of power." (PMID 23635032, 2013). "Because MDP increases NOD2 expression level and other NOD2 ligands also induce bone formation similarly to the action of MDP, NOD2 agonists like MDP could be a novel therapeutic agent of osteoporosis." (PMID 34071605, 2021). "The influence of NOD2 genotype on osteoporosis in CD has not been studied yet." (PMID 23635032, 2013).
osteosarcoma (4 papers, 2019 to 2025). A usually aggressive malignant bone-forming mesenchymal neoplasm, predominantly affecting adolescents and young adults. "A NOD2 agonist, mifamurtide, has already been approved in immunotherapy for patients with osteosarcoma, in combination with chemotherapy following complete surgical resection of the primary tumor." (PMID 30548868, 2019). "Specifically, NOD2 agonist mifamurtide certainly represents the most important compound to have been granted with marketing authorization by the European Medicine Agency for treating osteosarcoma in combination with other chemotherapeutics, following complete surgical removal of a primary tumor." (PMID 30548868, 2019). "Our data offer a mechanistic explanation for prior reports of the efficacy of MDP in a murine model of osteosarcoma, particularly as the investigators found that MDP was ineffective in Nod2–/– and Ccr2–/– mice." (PMID 39545417, 2024).
parasitic infection (4 papers, 2014 to 2024). "Increased concentrations of parasitic DNA in the intestines and brains of NOD2-/- mice indicated that the aggravation of intestinal and cerebral inflammation was due to enhanced susceptibility to parasitic infection." (PMID 25141224, 2014). "NOD2-/- mice presented higher parasitemia than C57BL/6 animals between the 21st and 30th day after infection." (PMID 32986710, 2020). "Enhanced parasitic infection and dissemination in NOD2-/- mice was accompanied by higher translocation rates of viable intestinal bacteria to extra-intestinal compartments such as liver, spleen, and kidney." (PMID 25141224, 2014). "Results of the present study indicate that NOD2 signaling is also essential for the protection of mice against intestinal parasite infection followed by systemic inflammation including the brain." (PMID 25141224, 2014). "In mammals, NOD1/NOD2 interacts with RIPK2, leading to the production of proinflammatory cytokines, to play roles in autophagy and anti-bacterial, -viral and -parasitic infections." (PMID 38715616, 2024). "Patent parasitemia was observed up to 40 and 50 days in the C57BL/6 and NOD2-/- infected mice, respectively." (PMID 32986710, 2020).
prostate carcinoma (4 papers, 2009 to 2022). A carcinoma that arises from epithelial cells of the prostate gland. "It has been reported that NOD2 has been linked to the innate immune response of prostate epithelial cells and the occurrence and progression of prostate cancer." (PMID 36386841, 2022). "In addition, we used qRT-PCR to compare the expression of hub genes (CHMP4C, GSDMB, NOD2, PLCG1, CYCS, GPX4) between prostate cancer cell lines (LNCap, PC3, DU-145) and the normal prostate epithelial cell line (RWPE-1)." (PMID 36386841, 2022).
Streptococcus pneumonia (4 papers, 2011 to 2017). "A known pathogen-associated molecular pattern recognized by NOD2 is muramyl dipeptide exhibited on the surfaces of Gram-positive bacteria, such as Streptococcus pneumonia." (PMID 28369145, 2017). "Streptococcus pneumonia, another intracellular pathogen upregulates the expression of NOD1 and NOD2, with NOD2 playing an important role in the activation of downstream signaling molecules, which coordinate the activation of NF-κB." (PMID 25722880, 2015). "As recently reported, NOD2 recognizes lysozyme-digested PGN processed by professional phagocytes and releases chemokine MCP-1/CCL2 to recruit additional monocytes/macrophages to restrict/clear Streptococcus pneumonia colonization in mice." (PMID 28165033, 2017). "In addition to TLRs, Pseudomonas aeruginosa and Streptococcal pneumonia can also be recognized by NOD1 and NOD2, respectively." (PMID 21886831, 2011).
AIDS (3 papers, 2013 to 2024). A syndrome resulting from the acquired deficiency of cellular immunity caused by the human immunodeficiency virus (HIV). "The nucleotide-binding oligomerization domain containing 2 (NOD2) gene has been identified previously as one linked to AIDs." (PMID 39430755, 2024). "A substantial contribution to the diagnosis derives from both the consideration of ethnicity and genotype analysis related to MEFV, MVK, TNFRSF1A, NLRP3, NLRP12, PSTPIP1, IL1RN, CARD15/NOD2, and PSMB8, which are the genes responsible for the syndromes collectively termed AIDs." (PMID 23971037, 2013).
allergic disease (3 papers, 2017 to 2020). An immune response that occurs following re-exposure to an innocuous antigen, and that requires the presence of existing antibodies against that antigen. "NOD1 and NOD2 promote Th1 and Th17 adaptive immunity by inducing the secretion of TNF and IL‐1107, 108 in addition to Th2 immune response, suggesting that signaling through these receptors may be central to susceptibility and exacerbation of allergies." (PMID 30891811, 2019).
Alzheimer disease (3 papers, 2009 to 2025). A progressive, neurodegenerative disease characterized by loss of function and death of nerve cells in several areas of the brain leading to loss of cognitive function such as memory and language. "Our research over the past decade has compellingly demonstrated the potential of Nucleotide-binding oligomerization domain-containing protein 2 (NOD2) receptor agonists in Alzheimer’s disease (AD) treatment." (PMID 37446081, 2023). "Distinct immune markers were found to differentiate FTD from Alzheimer’s disease (AD) and amyotrophic lateral sclerosis (ALS), with GFAP, SPARC, and SPP1 varying between FTD and AD and IL-15, HERV-K, NOD2, and CHIT1 differing between FTD and ALS." (PMID 40305176, 2025).
Anxiety (3 papers, 2021 to 2025). Intense feelings of nervousness, tension, or panic often arise in response to interpersonal stresses. "Indeed, in NOD2 knock-out mice, anxiety behaviours were observed with changes in serotonergic release leading to hyperactivation of the hypothalamic-pituitary-adrenal axis." (PMID 34072914, 2021).
autoimmune uveitis (3 papers, 2012 to 2023). An autoimmune form of uveitis (disease). "Thus, our data suggest that exogenous or endogenous molecules acting on both TLR2 and NOD2 on RACs might have an enhancing effect on susceptibility to autoimmune uveitis." (PMID 22808176, 2012).
bladder cancer (3 papers, 2022 to 2024). "We also observed that the NOD2 c.3020insC variant was more frequent in patients with bladder cancer aged between 51 and 60 years." (PMID 35478773, 2022). "The NOD2 c.3020insC allele did not play a significant role in the survival of patients with bladder cancer." (PMID 35478773, 2022). "In summary, the results of this study indicate that neither the NOD2 c.3020insC variant or the CDKN2A p.A148T polymorphism are associated with the survival of bladder cancer patients regardless of age, cancer family history, smoking status and sex." (PMID 35478773, 2022). "The study revealed that the presence of the NOD2 c.3020insC variant and the CDKN2A p.A148T polymorphism did not influence bladder cancer survival." (PMID 35478773, 2022). "Intriguingly, while NOD1 and NOD2 often function synergistically in various cellular mechanisms, our study revealed that MARCH7 exclusively interacted with NOD1 and not NOD2 in bladder cancer cells." (PMID 38462600, 2024).
cardiac hypertrophy (3 papers, 2022 to 2025). "NOD2 deficiency promoted cardiac hypertrophy and fibrosis by activating TLR4 and the MAPKs, NF-kB, and TGF-β/Smad pathways." (PMID 35990977, 2022). "Nucleotide-binding oligomerization domain-2 (NOD2)-knockdown in mice increases cardiac hypertrophy and fibrosis by upregulating multiple pathways, including the TLR4/NF-κB, TLR4/MAPK, and TGF-β/Smad pathways." (PMID 37113698, 2023). "NOD2-knockout mice develop significantly worsened cardiac hypertrophy and fibrosis under pressure overload, suggesting NOD2 signaling normally plays a protective role in attenuating cardiac remodeling by modulating multiple inflammatory and fibrotic signaling cascades." (PMID 40710377, 2025).
E. coli infection (3 papers, 2012 to 2022). "It has been documented that murine norovirus-1 activates NOD1 and NOD2 signaling, which can accelerate the secondary E. coli infection." (PMID 35873172, 2022). "Along the same line of investigation, mice deficient in NOD2 or both NOD1 and NOD2 have a delayed response to Gram-negative Citrobacter rodentium, a rodent surrogate of human enteropathogenic Escherichia coli infection." (PMID 24886810, 2014). "Nod-like receptor NOD1 in Caco-2 cells could prevent IκB kinase and NF-κB activation in response to enteroinvasive E. coli infection, whereas NOD2 is likely not important in signalling the onset of NF-κB activation." (PMID 22848393, 2012).
enterocolitis (3 papers, 2007 to 2020). An inflammatory process affecting the small intestine and colon. "To address this, we applied Nod2-deficient IL-10−/− (Nod2−/− IL-10−/−) mice and IL-10−/− counterparts both with a depleted intestinal microbiota to warrant pathogen-induced enterocolitis." (PMID 28752081, 2017). "In addition, secondary abiotic IL-10−/− mice deficient in the innate receptor nucleotide-oligonucleotide-domain 2 (Nod2) developed less severe enterocolitis upon peroral C. jejuni infection." (PMID 33261211, 2020).
glioblastoma (3 papers, 2022 to 2025). The most malignant astrocytic tumor (WHO grade IV). "In the present work, we have assessed the impact of NOD2 rs2066844 and rs2066845 variants in glioblastoma development." (PMID 35123435, 2022). "Our results showed a significant correlation between ATG2B rs3759601, ATG10 rs1864183 and NOD2 rs2066844 variants and higher risk to suffer glioblastoma." (PMID 35123435, 2022). "A study showed a significant correlation between nucleotide oligomerization domain 2 (NOD2) variants and a higher risk of glioblastoma." (PMID 36185204, 2022). "Here, we aimed to assess the potential association between several candidate polymorphisms in autophagy genes (ATG2B rs3759601, ATG16L1 rs2241880, ATG10 rs1864183, ATG5 rs2245214, NOD2 rs2066844 and rs2066845) and glioblastoma susceptibility." (PMID 35123435, 2022). "In this study, we have analyzed common polymorphisms in genes involved in autophagy (ATG2B rs3759601, ATG16L1 rs2241880, ATG10 rs1864183, ATG5 rs2245214, NOD2 rs2066844 and rs2066845) in order to evaluate their role in the susceptibility to suffer glioblastoma." (PMID 35123435, 2022). "This study investigates NOD2’s role in promoting glioblastoma through its effects on the epithelial–mesenchymal transition (EMT) and cancer stem cell (CSC) markers." (PMID 40868292, 2025). "Understanding the relationship between NOD2 and these key malignancy drivers could provide valuable insights into the glioblastoma pathogenesis and identify novel therapeutic opportunities." (PMID 40868292, 2025). "However, significant association with glioblastoma risk was found in ATG2B rs3759601, ATG10 rs1864183 and NOD2 rs2066844." (PMID 35123435, 2022). "To elucidate the functional role of NOD2 in the glioblastoma pathogenesis, we conducted phenotypic analyses following gene silencing in multiple GBM cell lines." (PMID 40868292, 2025). "While NOD2’s role in cancer progression has been established across multiple tumor types, no previous study has specifically investigated the relationship between NOD2 expression and EMT processes in glioblastoma progression." (PMID 40868292, 2025).
helminth infection (3 papers, 2016 to 2019). "For example, Nod2 knockout (KO) mice showed that intestinal helminth infection prevented the colonization of inflammatory Bacteriodes vulgatus and promoted the colonization of protective microbiota enriched in Clostridiales, which was caused by a T helper cell type 2 immune response." (PMID 28066436, 2016).